CTLA4 (cytotoxic T-lymphocyte associated protein 4)
Diseases named in the same sentence as CTLA4 in open-access papers (continued):
Sharing a sentence is not in itself a finding about the gene and the disease.
malaria (continued). "Levels of expression of the inhibitory markers PD-1 and CTLA-4 were upregulated in children with symptomatic malaria, confirming recent studies that have observed increased levels of PD-1 and CTLA-4 during acute infections, resulting in decreased production of cytokines." (PMID 31316497, 2019). "In this study, we found that CD4+PD-1+ and CD8+CTLA-4+ could also predict parasitemia levels in the asymptomatic malaria group." (PMID 31316497, 2019). "CTLA-4 was a good predictor of parasitemia in both symptomatic and asymptomatic malaria groups." (PMID 31316497, 2019). "Significantly, expression of CTLA-4 by T cells is increased in children only during severe malaria." (PMID 30631323, 2018). "Furthermore, chloroquine, a lysosomal inhibitor drug used against malaria, was found to augment CTLA-4 levels in vitro in Tregs and activated T-cells of LRBA-deficient patients." (PMID 28197149, 2017). "Importantly, patients with severe cerebral malaria showed a higher frequency of CTLA4+CD4+ T cells than patients with uncomplicated malaria." (PMID 27802341, 2016). "Indeed, we found that the PD1+CTLA4+CD4+ Teff cells in our malaria patients produced the regulatory cytokine IL10 in response to P. falciparum-antigens." (PMID 27802341, 2016). "High numbers of CD4+ T cells in the peripheral blood of malaria patients expressed CTLA4 and PD1." (PMID 27802341, 2016). "We therefore asked whether the malaria-induced PD1+CTLA4+CD4+ T cells could suppress other CD4+ T cells." (PMID 27802341, 2016). "Thus, the CTLA-4 and PD-1 inhibitory pathways have essential, independent and non-redundant roles in regulating the body's complex response to malaria." (PMID 22319445, 2012). "There may also be different roles for the major regulatory molecules produced by Treg cells in our study (CTLA-4) and inducible regulatory T cells identified by others (IL-10;), by acting on different cellular/tissue targets during malaria." (PMID 21170302, 2010). "Here, results of our univariate approaches could be confirmed by the multivariate analysis which identified a cluster group of T cells which was more frequent in children with complicated malaria than uncomplicated malaria and showed increased expression of CTLA-4, PD-1 and partially LAG-3." (PMID 29555909, 2018). "However, blockade of CTLA-4, LAG3 and PD-L1 was insufficient to restore control of S. Typhimurium infection, suggesting that additional effects of malaria on immunity to S. Typhimurium may be responsible for loss of vaccine-mediated protection." (PMID 26366739, 2015). "A study carried out in Fulani, a West African ethnic group with low susceptibility to malaria, reported that this population’s PBMCs express higher amounts of RNA for several Th1 and Th2 related genes but gene expression of FOXP3 and cytotoxic T lymphocyte antigen 4 (CTLA4) was markedly lower." (PMID 24642188, 2014). "Our study thus raises the intriguing hypothesis that in the our malaria model, CTLA-4 may be the primary regulatory pathway for CD4+ T cells, thereby indirectly affecting CD8+ T cell responses, whereas PD-1/PD-L1 preferentially and directly fulfils this role for CD8+ T cells." (PMID 22319445, 2012). "It is imperative to understand the immunological pathways through which high CTLA‐4 and TIM‐3 expression is able to delay the development of IFN‐γ+ T cell responses to malaria." (PMID 31605396, 2020). "We characterized the expression of PD-1, CTLA-4, CD28 and CD57 markers in children with symptomatic malaria, asymptomatic malaria and healthy controls." (PMID 31316497, 2019). "In this study, we phenotypically characterized the expression of T cell inhibitory(PD-1, CTLA-4) and senescent markers (CD28(-), CD57) from children with symptomatic malaria, asymptomatic malaria and healthy controls using flow cytometry." (PMID 31316497, 2019). "In contrast to the observation with CTLA-4 and PD-1, Tim-3 was more frequently expressed on CD4+ T cells in children with uncomplicated versus complicated malaria." (PMID 29555909, 2018).
malaria (continued). "The highest frequencies of CTLA-4+ and PD-1+CD4+ T cells were found in children with complicated malaria, supporting prior observation with children in endemic areas and adult malaria patients." (PMID 29555909, 2018). "Pearson correlation analysis showed that the PD1 expression correlated strongly with CTLA4 expression on CD4+ T cells (r = 0.83) in malaria patients." (PMID 27802341, 2016). "Flow cytometric analysis showed a more frequent expression of CTLA4 and PD1 on CD4+ T cells of malaria patients than of healthy control subjects." (PMID 27802341, 2016). "But our data support results from an earlier study with children in Ghana, in which a higher percentage of CTLA4+CD4+ T cells was observed in children with severe malaria, predominantly severe anemia, than in children with uncomplicated malaria." (PMID 27802341, 2016). "CTLA4 and PD1 expression on CD4+ T cells were also compared between patients with an uncomplicated course of malaria (n = 13) and patients with severe cerebral malaria (n = 3)." (PMID 27802341, 2016). "CD4+ T cells of the malaria patients were significantly more likely to express PD1 and CTLA4 than CD4+ T cells of the healthy volunteers (P<0.0001)." (PMID 27802341, 2016). "Our results corroborate observations by us and other groups in rodent malaria models that administration of antibodies against CTLA4 and/or PDL1 in vivo increases the proinflammatory T cell responses in murine malaria." (PMID 27802341, 2016). "It is interesting to note in this context that both IL-10 blockade and blockade of PDL-1, CTLA4 and LAG3 reduced the level of circulating malaria parasites, however only IL-10 blockade restored vaccine-mediated protection." (PMID 26366739, 2015). "T cells expressing multiple checkpoint markers, including PD‐1 and LAG‐3,137, 147, 148, 149, 150 CTLA‐4,149, 150, 151 OX40,151 and Tim‐3137, 149, 150, 152, 153 have been shown to be upregulated during infection with malaria in humans and contribute to immunosuppression." (PMID 39248154, 2024). "Additionally, higher proportions of Th1 cells also expressed CTLA-4, TIM-3, CD38 and ICOS during malaria." (PMID 37968278, 2023). "Thus, CTLA‐4 expression remains elevated among memory CD4+ T cells in both human and mouse asymptomatic malaria." (PMID 35475529, 2022). "Thus, malaria-induced CD8+ T cells co-express LAG-3, PD-1, TIGIT, TIM-3, CTLA-4, and CD39 but similarly express more effector molecules compared to those expressing lower levels of co-inhibitory molecules." (PMID 35874786, 2022). "In contrast to the findings with an increased expression of CTLA-4 and PD-1, the frequencies of GrzB+ or CD39+ CD4+ T cells were selectively increased in children with uncomplicated malaria, compared to children with complicated malaria." (PMID 29555909, 2018). "However, that suppressive effect is limited to malaria-specific and polyclonal stimulation of PD1+CTLA4+CD4+ T cells." (PMID 27802341, 2016). "Blocking both, CTLA4 and PDL1, enhanced the T cell proliferation in 4 of 11 malaria patients." (PMID 27802341, 2016). "Other factors such as the duration of antigen exposure or cytokine levels might additionally influence the CTLA4 and PD1 expression in malaria." (PMID 27802341, 2016). "We initially hypothesized that the induction of coinhibitory receptors, primarily CTLA4 and PD1, is an important and adaptable mechanism by which CD4+ T cell responses in malaria are downregulated." (PMID 27802341, 2016). "Increased proportions of CD4+ T cells express CTLA-4, OX40, Glucocorticoid-induced TNFR family related gene (GITR), tumor necrosis factor alpha receptor type II (TNFRII), PD-1, LAG3, T-cell immunoglobulin and mucin-3 (TIM3) and CD69 during P. vivax and P. falciparum malarias." (PMID 30631323, 2018).
malaria (continued). "The here identified T cell cluster which was more abundant in children with complicated malaria showed an increased expression of CTLA-4, PD-1 and partially LAG-3, but did not belong to the group with the highest expression levels of these co-inhibitory molecules." (PMID 29555909, 2018). "Interestingly, isolated PD1+CTLA4+CD4+ T cells acted like antigen-specific Tr1-like cells: they suppressed the P. falciparum-specific and anti-CD3/28-induced proliferation of the CD4+ T cell population from malaria patients." (PMID 27802341, 2016). "As the blockade of CTLA4 and PD1/PDL1 enhanced the proliferative response of PBMC to P. falciparum in some malaria patients, we used these blocking antibodies to assess whether these coinhibitory receptors participate in the suppressive role of PD1+CTLA4+CD4+ T cells." (PMID 27802341, 2016). "Using a co-culture system of malaria-infected red blood cells (iRBCs) and peripheral blood mononuclear cells from healthy individuals, we found that two populations of Foxp3hi and Foxp3int CD4+CD25hi T cells with a typical Treg phenotype (CTLA-4+, CD127low, CD39+, ICOS+, TNFRII+) were induced." (PMID 19680449, 2009). "Of note, malaria patients also showed a higher percentage of Foxp3+CD4+ Tregs than healthy controls but frequencies of Foxp3+ Tregs and PD1+CTLA4+ CD4+ T cells did not correlate." (PMID 27802341, 2016). "Thus, CTLA-4 and PD-1/PD-L1 play essential, independent and non-redundant roles in preventing ECM in resistant animals; this reinforces the urgent need to compare the activation and down-stream effects of these pathways in humans with or without severe malaria pathology." (PMID 22319445, 2012).
pancreatitis (25 papers, 2016 to 2025). Inflammation of the pancreas. "Combination ICI therapy, particularly the use of anti-CTLA-4 agents in combination with PD-1/PD-L1 inhibitors, has been associated with a higher incidence of pancreatitis compared to monotherapy." (PMID 39347217, 2024). "However, the association between different ICIs and pancreatitis remains controversial, as some other studies have demonstrated that both anti-CTLA4 alone and combination treatments with nivolumab and ipilimumab are associated with a higher incidence of pancreatitis than anti-PD-1/PD-L1 alone." (PMID 35431928, 2022). "Similar to how CTLA-4 polymorphism predisposes an individual to IBD, it is possible that a similar relationship exists between CTLA-4 and pancreatitis in humans that is exacerbated in ICI therapy, resulting in AIP-3." (PMID 40364113, 2025). "Although there are no reports on differences in incidence rates among drug classes, combination therapy with PD-1 and CTLA-4 inhibitors increases the incidence of pancreatitis as an irAE." (PMID 40423705, 2025). "Several studies have shown that the prevalence of pancreatitis in ICIs therapy using anti-CTLA4 alone or in conjunction with nivolumab and ipilimumab is higher than that using PD-1/PD-L1 alone." (PMID 40176908, 2025). "These rates were consistent with previous studies reporting rates of pancreatitis (CTLA-4: 0.9–3%, PD-1: 0.5–1.6%, CTLA4 + PD-1: 1.2–2.1%)." (PMID 37359551, 2023). "The median time from immunotherapy initiation to the onset of pancreatitis ranges from 2 to 5 months (69 days for CTLA-4 inhibitor, 146 days for PD-1/PD-L1 inhibitor, and 110 days for combination therapy)." (PMID 35967881, 2022). "The incidence rate of ICI-related pancreatitis ranges from 2-8% (2% with CTLA-4 inhibitor, 4% with PD-1/PD-L1 inhibitor, and 8% with combination therapy)." (PMID 35967881, 2022). "PD-1 and PD-L1 may be markers predicting the risk of infectious complications in AP patients, and elevated CTLA-4 and PD-1 expression levels may prevent early pancreatitis." (PMID 36133806, 2022). "Moreover, incidence of grade 2 pancreatitis in CTLA-4-PD-1 combination group was 10.6%, significantly higher compared with that of mono-immunotherapy." (PMID 33732647, 2021). "The risk of pancreatitis was not significantly elevated under CTLA-4 and PD-1 inhibitors alone or in combination." (PMID 29971244, 2018). "Furthermore, among ICI, durvalumab affects the immune response at a later stage compared to anti-CTLA-4 and anti-PD-1, which may explain the rarity of anti-PD-L1 related pancreatitis." (PMID 35866825, 2022). "Some previous studies showed that the risk of pancreatitis was higher with anti-CTLA-4 than that with anti-PD-1 or anti-PD-L1, while another study found that anti-PD-L1 versus anti-PD-1 or anti-CTLA-4 was associated with a slightly increased connection of pancreatitis." (PMID 35431928, 2022). "However, neither CTLA-4 nor PD-1 inhibitor when given alone or in combination increased the risk of immune-induced pancreatitis when compared to controls." (PMID 29971244, 2018). "Interestingly, this meta-analysis demonstrated that both CTLA-4 inhibitors alone and combination treatment of PD-1 could increase the risk of amylase or lipase elevation but not significantly increase the risk of pancreatitis." (PMID 35866825, 2022). "We found that the CTLA-4 inhibitor increased the risk of lipase elevation (all-grade); however, neither CTLA-4 nor PD-1 inhibitor increased the risk of pancreatitis." (PMID 29971244, 2018). "Our meta-analysis has demonstrated that both CTLA-4 inhibitors alone and combination treatment of nivolumab and ipilimumab could increase the risk of amylase or lipase elevation, but not significantly increase the risk of pancreatitis when compared with controls." (PMID 29971244, 2018). "CNVs on CTLA-4 were eliminated from the forest plot for pancreatitis due to lack of data." (PMID 35053465, 2022).
pancreatitis (continued). "In nearly all the subgroups, we found the low overall heterogeneity of grade 1–5/3–5 pancreatitis, amylase, and lipase elevation incidence which displayed I2 values of 0.0%, but not in this subgroup (CTLA-4 inhibitor subgroup versus chemotherapy/placebo: I2 = 56.8%, p = 0.128)." (PMID 29971244, 2018).
sarcoidosis (25 papers, 2014 to 2025). Sarcoidosis is a multisystemic disorder of unknown cause characterized by the formation of immune granulomas in involved organs. "Granulomatous reactions, including sarcoidosis or sarcoid-like reactions have been associated with anti-CTLA-4 and anti-PD-1/PD-L1 therapy with onset anywhere from two weeks to two years." (PMID 36938327, 2023). "Another study reports correlations of specific CTLA-4 gene polymorphisms in sarcoidosis patients with different disease phenotypes." (PMID 25191698, 2014). "Interestingly, cancer treatment with anti-PD-1 or CTLA4-immune checkpoint blockade can cause a drug-induced sarcoidosis-like disease, further highlighting the link between aberrant T cell activation and sarcoidosis." (PMID 38715030, 2024). "Although the pathogenic mechanism of sarcoidosis induced by ICIs is unknown, it is worth noting that a decreased CTLA4 expression in Tregs and Th17 lymphocytes has been identified in patients with sarcoidosis." (PMID 34203101, 2021). "The contribution of the Th17 cell lineage to the pathophysiology of sarcoidosis is also supported by our recent identification of reduced cytotoxic T lymphocyte-associated protein 4 (CTLA4) expression on Th17 lineage cells, which may contribute to their increased activation." (PMID 34054347, 2021). "Although rare, sarcoidosis-like granulomatous reactions have been described in patients on anti-CTLA-4 and anti-PD-1 immunotherapy." (PMID 40103819, 2025). "Whereas proportions of Tregs expressing CD28 were high and unaltered, the fractions of CTLA4+ and PD-1+Tregs were increased in sarcoidosis, compared with HCs." (PMID 38715030, 2024). "Of note, blocking CTLA-4 to breach immune tolerance in cancer therapy can lead to granulomatous disease-mimicking sarcoidosis." (PMID 39431514, 2024). "CD56+CTLA4+ were higher in sarcoidosis than in GPA, MPA and HC (p = 0.0085, p = 0.0042 and p = 0.0004, respectively)." (PMID 36613701, 2022). "CTLA4+NK cells clustered for 100% of sarcoidosis patients, according to the decision tree analysis, while PD1+CD4 and CD8 cells clustered for 100% of GPA patients." (PMID 36613701, 2022). "Our study described, for the first time, increased PD1, TIGIT and CTLA4 expression on CD4 cells of sarcoidosis patients." (PMID 36613701, 2022). "CD4+CTLA4+ cell percentages were significantly higher in sarcoidosis than in MPA (p = 0.0079) and HC (p = 0.0117), and numerically higher than GPA (p = 0.0482)." (PMID 36613701, 2022). "CTLA4+NK cells clustered for 100% of sarcoidosis patients according to decision tree analysis, while PD1+CD4 and CD8 cells for clustered for 100% of GPA patients." (PMID 36613701, 2022). "In an interesting study, decreased CTLA-4 expression was demonstrated in both Th17 and Tregs in patients with sarcoidosis, but only Th17 cell numbers were increased." (PMID 36543347, 2022). "CD56+CTLA4+ were higher in sarcoidosis than GPA, MPA and HC (p = 0.0085, p = 0.0042 and p = 0.0004, respectively)." (PMID 36613701, 2022). "A number of cases of sarcoidosis or sarcoid-like reactions induced by ICIs have been reported in the recent literature, with anti-CTLA4 or anti-PD1 being used more frequently than anti-PDL1 or combination therapy." (PMID 34203101, 2021). "The pathogenetic mechanism of ICI-induced sarcoidosis is not well understood, but it is of note that decreased expression of CTLA4 in Tregs and Th17 cells has been reported in patients with sarcoidosis." (PMID 32403289, 2020). "Another case report describes two separate cases of sarcoidosis developing in the wake of receiving anti-PD-1 and anti-CTLA-4 therapy, either simultaneously, or sequentially." (PMID 30064495, 2018). "In a potential link with anti-CTLA4 therapy and sarcoidosis development, bronchoalveolar lavage samples and lung biopsy specimens from patients with sarcoidosis also contain high numbers of Th17 effector CD4+ cells." (PMID 28031822, 2016).